SEC23A (SEC23 homolog A, COPII component)
Description:
Component of the coat protein complex II (COPII) which promotes the formation of transport vesicles from the endoplasmic reticulum (ER). The coat has two main functions, the physical deformation of the endoplasmic reticulum membrane into vesicles and the selection of cargo molecules for their transport to the Golgi complex. Required for the translocation of insulin-induced glucose transporter SLC2A4/GLUT4 to the cell membrane (By similarity).
Synonyms: hSec23A; CLSD
Tractability: Small molecule: a structure with a bound ligand is known. Antibody: UniProt places it where antibodies can reach, with high confidence. PROTAC: ubiquitination databases record sites on it; its protein half-life has been measured.
Gene: Protein-coding gene on chromosome 14 (39,031,918 to 39,109,646, reverse strand). Ensembl gene ENSG00000100934.
Subcellular location: Cytoplasmic vesicle, COPII-coated vesicle membrane; Endoplasmic reticulum membrane; Cytoplasm, cytosol
Subcellular location (Human Protein Atlas): Cytosol; Endoplasmic reticulum
Pathways (Reactome):
Immune System: Antigen Presentation: Folding, assembly and peptide loading of class I MHC; MHC class II antigen presentation
Vesicle-mediated transport: COPII-mediated vesicle transport; Cargo concentration in the ER
Disease: SARS-CoV-2 activates/modulates innate and adaptive immune responses
Metabolism: Regulation of cholesterol biosynthesis by SREBP (SREBF)
Gene Ontology:
Molecular function: protein binding; zinc ion binding; GTPase activator activity
Biological process: COPII-coated vesicle cargo loading; COPII-coated vesicle budding; endocytic recycling; endoplasmic reticulum to Golgi vesicle-mediated transport; intracellular protein transport
Cellular component: COPII vesicle coat; cytosol; endoplasmic reticulum; endoplasmic reticulum exit site; endoplasmic reticulum membrane; ER to Golgi transport vesicle membrane; COPII-coated ER to Golgi transport vesicle; Golgi membrane; perinuclear region of cytoplasm
Genetic constraint (gnomAD): Loss-of-function variants: 35 observed, 65.55 expected, observed/expected ratio (o/e) 0.53, 90% interval 0.41 to 0.71. The upper end of that interval is the gene's LOEUF score, 0.71, which puts it in group 2 of 6, group 1 being the genes least tolerant of losing a copy. Missense variants: 550 observed, 696.43 expected, observed/expected ratio (o/e) 0.79, 90% interval 0.74 to 0.85. Synonymous variants: 209 observed, 225.55 expected, observed/expected ratio (o/e) 0.93, 90% interval 0.83 to 1.04.
Homologues: Orthologues: chimpanzee SEC23A (99% identical), macaque SEC23A (99% identical), dog SEC23A (99% identical), guinea pig SEC23A (99% identical), rabbit SEC23A (99% identical), mouse Sec23a (99% identical), rat Sec23a (99% identical), tropical clawed frog sec23a (93% identical), zebrafish sec23a (91% identical), Drosophila melanogaster Sec23 (75% identical), Caenorhabditis elegans sec-23 (60% identical). Paralogues in human: SEC23B (85% identical).
Diseases named in the same sentence as SEC23A in open-access papers:
SEC23A is named in the same sentence as 48 diseases in open-access papers, as found by Europe PMC text mining. Sharing a sentence is not in itself a finding about the gene and the disease. The quoted sentences say what the papers report.
breast carcinoma (10 papers, 2013 to 2020). "Another study revealed that elevated miR-200s family levels are associated with increased risk of metastasis in breast cancer and promotes metastatic colonization in mouse models through direct targeting of sec23a." (PMID 32708601, 2020). "In contrast, downregulated SEC23A expression was associated with poor disease relapse-free survival (RFS) of breast cancer patients, indicating that SEC23A might be a potential tumor metastasis suppressor." (PMID 31595159, 2019). "In fact, endogenous SEC23A was lower in highly metastatic breast cancer cells than in lowly metastatic cells." (PMID 31595159, 2019). "Taken together, both clinical and animal data demonstrates that SEC23A plays a key role in the inhibition of breast cancer metastasis." (PMID 31595159, 2019). "Several of these genes are extracellular factors and one of them (SEC23A) has been found to control secretion of anti-tumour factors in breast cancer." (PMID 27124473, 2016). "Further, miR-200 had pro-metastatic activity in a mouse model of breast cancer metastasis by targeting Sec23a, a suppressor of metastasis." (PMID 23626803, 2013). "Interestingly, SEC23A has a clear inhibitory role in breast cancer metastasis, especially the step of colonization during tumor cell metastasis but not at the step of tumor cell migration." (PMID 31595159, 2019). "Knockout of SEC23A could increase breast cancer colonization and reduce tumor cell migration, where these two effects of SEC23A may cancel each other out." (PMID 31595159, 2019). "Previous reports show that miR-200 could promote breast cancer metastatic colonization by targeting Sec23a." (PMID 27191272, 2016). "Moreover, as a direct target of miR-200s, Sec23A suppresses metastatic colonization and migration in breast cancer by mediating secretion of metastasis-suppressive proteins." (PMID 27495250, 2016). "In contrast, the miR-200 family members have been shown to enhance the migration ability of breast cancer cells and to promote the metastatic colonization of breast cancer cells through up-regulating the expression of E-cadherin and down-regulating that of ZEB2 and Sec23a." (PMID 27484639, 2016).
prostate carcinoma (9 papers, 2014 to 2025). A carcinoma that arises from epithelial cells of the prostate gland. "SEC23A expression was also reported to be associated with the resistance of prostate cancer to docetaxel treatment." (PMID 31595159, 2019). "SEC23A is known to be downregulated in prostate cancer, and its loss is a driver for metastasis." (PMID 34831007, 2021). "We show that miR-1227, which is enriched in L-EV from prostate cancer cells and induces migration of poorly migratory cancer cells, targets SEC23A to induce the shedding of L-EV, while possibly inhibiting the shedding of S-EV." (PMID 34831007, 2021). "Apart from RASD1 and ER-α, Sec23A was considered as a potential target for the current study based on preclinical data in breast and prostate cancer." (PMID 33255991, 2020). "Because SEC23A has been validated as a miR-375 target in a human prostatic carcinoma cell line, we further validated SEC23A expression at the protein level in MTC by immunoblotting and immunohistochemistry." (PMID 27036030, 2016). "A recent study has shown that miR-375 is an oncogenic miRNA and targets the Sec23A tumor suppressor gene in prostate cancer." (PMID 24173286, 2014). "Interestingly, the inhibition of SEC23A has been shown to promote prostate cancer metastasis through alterations in the secretome." (PMID 34831007, 2021). "Using an approach combining transcriptome analyses of miR-375 activation and inhibition as well as data exploration of the Cancer Cell Line Encyclopedia (CCLE) transcriptome database, we established SEC23A as a reliable miR-375 target, in accordance with previous reports in prostate carcinomas." (PMID 27036030, 2016). "We focused on SEC23A because it was consistently reduced at the protein level, in response to stable expression of miR-1227 in RWPE-2 and PC3 prostate cancer, as well as in U87 glioma cell lines." (PMID 34831007, 2021). "Importantly, the inhibition of SEC23A has been shown to promote prostate cancer metastasis, and SEC23A expression is decreased in tumor tissues of patients with metastatic castration-resistant disease, in comparison to primary prostate cancer and benign tissue." (PMID 34831007, 2021). "Sec23A was predicted by DIANA and validated in previous studies in breast and prostate cancer." (PMID 33255991, 2020). "In addition, we examined expression levels of the two miR-375 target genes (SEC23A and YAP1) and observed significant reduction in the expression at both protein and mRNA levels in miR-375 transfected prostate cancer cell lines." (PMID 27832783, 2016).
melanoma (8 papers, 2020 to 2026). A malignant, usually aggressive tumor composed of atypical, neoplastic melanocytes. "Furthermore, Sec23a and Atg5 are favorable diagnostic and prognostic markers for human melanoma and colon cancer." (PMID 32811814, 2020). "We also confirmed the direct binding of BBF2H7 to the Sec23a promoter in a B16 melanoma cell line treated with α-MSH." (PMID 41516372, 2026). "We have shown previously that Sec23a inhibits metastatic colonization efficiency of melanoma by regulating the transportation of secretory proteins." (PMID 37356089, 2023). "Recent studies have demonstrated that SEC23A inhibits melanoma metastasis via autocrine activation of autophagy in extravasated tumor cells and inhibition of the MAPK signaling pathway." (PMID 37670384, 2023). "Previous studies have demonstrated that SEC23A increases autophagy by promoting S100A8 autocrine in melanoma." (PMID 37670384, 2023). "Next, Pearson correlation analysis combined with clinical evaluation using human melanoma data (TCGA‐SKCM) was performed to analyze the correlation between SEC23A, SPARC, and the 67 candidate gene targets of miR‐487a‐5p (Fig. 4Aa‐b)." (PMID 37356089, 2023). "Consistent with the literature, we show that Sec23a inhibits metastatic colonization efficiency by changing the secretome to activate autophagic activity in melanoma cells." (PMID 35236368, 2022). "In this present study, using stable CSCs derived from human melanoma cell lines M14 and A375, we show for the first time that Sec23a inhibits the self-renewal of melanoma CSCs via inactivation of ER-phagy." (PMID 35236368, 2022). "To assess the clinical relevance of our novel finding that Sec23a inhibits the self-renewal of melanoma CSCs, we performed clinical data analysis using the TCGA (The Cancer Genome Atlas)." (PMID 35236368, 2022). "In the present study, by employing stable CSC cell lines derived from human melanoma cell lines M14 and A375, we show for the first time that Sec23a inhibits the self-renewal of melanoma CSCs via inactivation of ER-phagy." (PMID 35236368, 2022). "By employing the stable CSC cell lines derived from human melanoma cell lines M14 and A375, we show for the first time that Sec23a inhibits the self-renewal of melanoma CSCs via inactivation of ER-phagy." (PMID 35236368, 2022). "We further show that S100A8 transported by SEC23A inhibits melanoma metastatic colonization via autocrine activation of autophagy in extravasated tumor cells, thus have identified for the first time the link between Sec23a and autophagy." (PMID 35236368, 2022). "Here we show that PF4 and SPARC in the Sec23a-regulated secretome can act cooperatively to inhibit melanoma metastasis." (PMID 34421345, 2021). "Taken together, these results indicate that secreted PF4 acts downstream Sec23a to mediate its inhibition of melanoma cell migration and invasion in vitro." (PMID 34421345, 2021). "While few published studies reported the tumor suppressor function of SEC23A in breast, prostate, melanoma, colorectal cancer, mechanistic understanding is limited." (PMID 34456965, 2021). "In this study, we first assessed the relationship between the Sec23a expression status and the metastatic behavior of melanoma cells in vitro." (PMID 34421345, 2021). "In summary, these observations show that Sec23a inhibits the metastatic ability of melanoma cells in vitro." (PMID 34421345, 2021). "SEC23A inhibits the self‐renewal of melanoma CSCs by inactivating ER phagocytosis." (PMID 40042106, 2025). "In our previous studies, we show that miR-200c augments melanoma metastasis by targeting Sec23a." (PMID 35236368, 2022). "First, the inhibitory effect of Sec23a on melanoma metastasis is mediated by secreted PF4." (PMID 34421345, 2021). "We next investigated whether the inhibitory effect of SEC23A on melanoma cell invasion is mediated by secreted PF4." (PMID 34421345, 2021).
melanoma (continued). "Few published studies by others have shown an inhibitory role of SEC23A in human cancer progression thus its expression is correlated with favorable clinical outcomes including prostate cancer, colorectal cancer, melanoma, and breast cancer." (PMID 34456965, 2021). "Given the data showing that Sec23a inhibited metastatic colonization and activated autophagy in melanoma cells, we next evaluated whether anti-metastatic colonization effect of Sec23a is dependent on autophagy using M14 derivative OL and POL cells." (PMID 32811814, 2020). "Thus, our prior work suggests an inhibitory role of Sec23a in melanoma metastasis." (PMID 34421345, 2021). "The present study has made a set of novel findings to elucidate a new CSC self-renewal mechanism that has not been described before, i.e., Sec23a inhibits the stemness of melanoma CSCs by inactivation of ER-stress induced ER-phagy." (PMID 35236368, 2022). "Specifically, platelet factor-4(PF4) transported by SEC23A, may cooperate with another secreted protein acidic and rich in cysteine (SPARC) to inhibit melanoma metastasis via inhibition of MEPK/ERK activation." (PMID 34421345, 2021). "The most important finding of the current study is that PF4 transported by SEC23A, may cooperate with another secretory protein SPARC to inhibit melanoma metastasis via inhibition of MEPK/ERK activation." (PMID 34421345, 2021).
colorectal cancer (6 papers, 2016 to 2025). A primary or metastatic malignant neoplasm that affects the colon or rectum. "In vitro SEC23A expression suppressed proliferation and metastasis of breast, prostate, and colorectal cancer cells." (PMID 31595159, 2019). "In addition, a recent study revealed that miR-21 expression enhanced colorectal cancer cell proliferation and metastasis by targeting and inhibiting SEC23A expression." (PMID 31595159, 2019). "Moreover, knockdown of SEC23A, a GTPase-activating protein critical for protein trafficking, has been shown to increase the proliferation, migration, and invasion of colorectal cancer cells." (PMID 28640862, 2017).
cataract (4 papers, 2010 to 2025). Partial or complete opacity of the crystalline lens of one or both eyes that decreases visual acuity and eventually results in blindness. "SEC23A mutations have been reported to cause craniolenticulosutural dysplasia, a disease characterized by craniofacial and skeletal malformation such as delay in closure of fontanels, sutural cataracts and facial dysmorphisms, due to defective collagen secrection." (PMID 29343764, 2018). "This study not only expands the genotypic and phenotypic spectrum of the SEC23A gene but also highlights congenital cataracts as a typical sign of ARCLSD." (PMID 37828500, 2023). "Conversely, lesions in the SEC23A protein, which directly binds to SARA2, cause cataracts and skeletal malformations in CLSD (cranio-lenticulo-sutural dysplasia) patients." (PMID 20442775, 2010).
anemia (3 papers, 2021 to 2023). A reduction in the number of red blood cells, the amount of hemoglobin, and/or the volume of packed red blood cells. "Whereas mutations in the SEC23B gene are responsible for CDA II, mutations in SEC23A result in cranio-lenticulo-sutural dysplasia, a disease characterized by bone abnormalities, in absence of anemia." (PMID 37373084, 2023). "SEC23B-deficient mice pups are born with no obvious anemia and die shortly after birth, whereas SEC23A-deficient animals die during mid-embryogenesis with defects in neural tube closure and extraembryonic membrane formation." (PMID 37373084, 2023). "Mice with erythroid-specific SEC23A deficiency exhibited no anemia." (PMID 34818036, 2021). "Our data strongly support the concept that increasing the expression of the SEC23A gene may prove a novel therapeutic strategy for CDA II not only for the treatment of anemia but also of the iron overload that remains the most harmful complication of this condition." (PMID 35163229, 2022).
bladder cancer (3 papers, 2021 to 2025). "Next, we performed bioinformatic virtual analysis to objectively derive mechanisms underlying the oncogenic activity of SEC23A in human bladder cancer (section “Materials and Methods”)." (PMID 34456965, 2021). "Therefore, the correlations of TME with SEC23A is not the mechanism that underlies the independent poor prognosis of SEC23A in bladder cancer." (PMID 34456965, 2021). "While MAPK activation often leads to increased cell proliferation, bladder cancer exploits the SEC23A-regulated MAPK signaling to enhance the more invasive behavior of cancer cells to confer a poor prognosis of SEC23A in bladder cancer." (PMID 34456965, 2021). "Further, we analyzed the association between SEC23A expression and the changes in TIIC concentration in a bladder cancer sample via the CIBERSORT and observed a weak association that was not statistically significant." (PMID 34456965, 2021). "Multivariate analysis has discovered that SEC23A expression is an independent poor prognostic factor in bladder cancer." (PMID 34456965, 2021). "Next, we found MEF2A gene expression in advanced tumor samples was significantly higher than that in early stage tumor samples, consistent with the oncogenic role of SEC23A in bladder cancer." (PMID 34456965, 2021). "Using the T24 human bladder cancer cell line, we confirmed that silencing of SEC23A expression inhibited the MAPK signaling pathway and MEF2A expression." (PMID 34456965, 2021). "To confirm the oncogenic activity of SEC23A we identified through bioinformatics analyses in bladder cancer, the widely used human bladder cancer cell line T24 with SEC23A overexpression or silencing was successfully constructed." (PMID 34456965, 2021). "SEC23A has been indicated as a potential prognostic marker in bladder cancer." (PMID 40728965, 2025). "As a proof of principle, we applied this framework and derived the clinical relevance of SEC23A in human cancer, especially in bladder cancer, identified SEC23A as a poor prognostic marker of bladder cancer, and predicted MAPK signaling as the mediator of the oncogenic activity of SEC23A." (PMID 34456965, 2021). "Next, we performed KM analysis of SEC23A expression level and survival in bladder cancer patients." (PMID 34456965, 2021). "Thus, in the present study, we focused our validation on the oncogenic role of SEC23A in bladder cancer." (PMID 34456965, 2021). "We used GESA to identify SEC23A-correlated molecular pathways in bladder cancer." (PMID 34456965, 2021). "Using this framework to analyze the clinical relevance of SEC23A, we have discovered the prognostic potential of SEC23A in different cancers and identified SEC23A as an independent prognostic factor for poor prognosis in bladder cancer, which implicates SEC23A, for the first time, as an oncogene." (PMID 34456965, 2021). "Combined, these findings suggest that SEC23A can serve as an interesting novel prognostic biomarker in STAD, similar to what has previously been suggested for bladder cancer." (PMID 37046730, 2023).
congenital cataracts (3 papers, 2023 to 2024). "Cranio-lenticulo-sutural dysplasia (CLSD, OMIM #607812) is a rare genetic condition characterized by late-closing fontanels, skeletal defects, dysmorphisms, and congenital cataracts that are caused by bi-allelic or monoallelic variants in the SEC23A gene." (PMID 38275611, 2024). "CLSD (OMIM #607812) is a syndrome characterized by facial dysmorphism, late-closing fontanels, congenital cataracts, and skeletal defects caused by monoallelic or biallelic mutations in the Sec23A gene." (PMID 39101946, 2024).
Congenital dyserythropoietic anemia type II (3 papers, 2016 to 2025). Congenital dyserythropoietic anemia type II (CDA II) is the most common form of CDA (see this term) characterized by anemia, jaundice and splenomegaly and often leading to liver iron overload and gallstones. "Previous research has demonstrated that SEC23B mutations may cause congenital dyserythropoietic anemia type II (CDAII), while the mutations of SEC23A may cause cranio-lenticulo-sutural dysplasia (CLSD)." (PMID 37046730, 2023).